PTPN13 (protein tyrosine phosphatase non-receptor type 13)
Diseases named in the same sentence as PTPN13 in open-access papers (continued):
Sharing a sentence is not in itself a finding about the gene and the disease.
colorectal cancer (11 papers, 2008 to 2026). A primary or metastatic malignant neoplasm that affects the colon or rectum. "Conversely, the E2455D and Y2260WX SNPs in the catalytic domain of PTPN13 that have been identified in colorectal cancer induce a loss of 50 to almost 100%, respectively, of the phosphatase activity." (PMID 33322542, 2020). "The Y2081D Tyr2081Asp (T > G), rs989902 (rs for SNP reference), in exon 39, near the PTPN13 phosphatase domain, is associated with colorectal cancer in Polish patients (relative risk compared to the “wild-type” genotype: 2.087), and with HNSCC in American patients (Odds Ratio, OR, =1.26)." (PMID 33322542, 2020). "Mutated PTPN13 was suggested to be a tumor suppressor gene in colorectal cancer." (PMID 32536826, 2020). "Moreover, in a large study on colorectal carcinoma, PTPN13 was identified as one of the three most frequently mutated PTPs and some of these PTPN13 mutations were also found in tumors from other tissues." (PMID 29221157, 2017). "A meta-analysis of data from Caucasian and Asian patients confirmed its association with HNSCC (OR = 1.23), but a protective role was attributed to PTPN13 in colorectal cancer (OR = 0.51)." (PMID 33322542, 2020). "miR-200b, ZEB2, and PTPN13 are downregulated in colorectal carcinoma with serosal invasion." (PMID 36556168, 2022). "Previous studies on the mutational analysis of the tyrosine phosphatase gene superfamily in human cancers identified 83 somatic mutations in six PTPs (PTPRF, PTPRG, PTPRT, PTPN3, PTPN13, PTPN14), affecting 26% of colorectal cancers and a smaller fraction of lung, breast and gastric cancers." (PMID 27833130, 2016). "Finally, systematic mutational analysis of the human PTP gene super family identified somatic mutations in six PTPs (PTPRF, PTPRG, PTPRT, PTPN3, PTPN13, PTPN14), affecting 26% of colorectal cancers." (PMID 19000305, 2008). "Conversely, sequencing of PTPN13 exon 7, which could be involved in the regulation of FAS-related apoptosis, in 103 colorectal cancer samples did not reveal any mutation." (PMID 33322542, 2020).
hepatocellular carcinoma (11 papers, 2013 to 2026). A malignant tumor that arises from hepatocytes. "For instance, PTPN13 gene mutations have been identified in colorectal, head and neck, and hepatocellular carcinoma." (PMID 24191246, 2013). "Furthermore, studies in ovarian 57, prostate 48 and hepatocellular carcinoma 24 showed loss of PTPN13 expression in tumor versus normal tissues, in high grade versus low grade tumors, and a correlation between PTPN13 expression and favorable prognosis, respectively." (PMID 31938048, 2020). "PTPN13 overexpression was also correlated to lower cell proliferation rates in hepatocellular carcinoma and clear renal cell carcinoma." (PMID 34265306, 2021). "PTPN13 inhibited hepatocellular carcinoma through inactivation of the epidermal growth factor receptor (EGFR)/extracellular signal-regulated kinase (ERK) signaling pathway." (PMID 30001383, 2018). "While this study focuses on hepatocellular carcinoma, the mechanisms described could potentially apply to other types of cancer, including head and neck cancer, as PTPN13 is also involved in head and neck squamous cell carcinoma." (PMID 37760479, 2023). "Here, we found that HBx downregulated PTPN13 expression in hepatoma cells." (PMID 33051595, 2021). "Taken together, these results prove that HBx downregulates PTPN13 expression via epigenetic silencing and that DNMT3A physically binds to the PTPN13 promoter at a site −343 to −313 bp upstream of the transcription start site, leading to DNA methylation in hepatoma cells." (PMID 33051595, 2021). "This study suggests that the hepatitis B virus X protein (HBx) plays a significant role in the progression of hepatocellular carcinoma (HCC) and highlights the role of a protein called PTPN13, which is known to regulate FAS-induced apoptosis and NGFR-mediated proapoptotic signaling negatively." (PMID 37760479, 2023).
ovarian carcinoma (8 papers, 2015 to 2024). A malignant neoplasm originating from the surface ovarian epithelium. "The PTPN13 gene encodes the PTPN13, which is a negative regulator of tumor growth in human breast and ovarian cancer, but its pathological role in CML and tumor sensitivity in tyrosine kinase inhibitors are not known." (PMID 34030730, 2021). "EMT, which is induced by PTPN13 KO/KD in our model, plays an important role in platinum salt resistance in various tumor types, including ovarian cancer." (PMID 37895093, 2023). "PTPN family members almost contribute to the progression of ovarian cancer, except for PTPN13." (PMID 35957898, 2022). "However, two studies only on HGSOC, the most frequent ovarian cancer subtype, highlighted a correlation between high PTPN13 protein and mRNA expression and better prognosis in 97 and 58 HGSOC samples, respectively (p = 0.042 and p = 0.03)." (PMID 33322542, 2020). "However, Reed's group found an association between PTPN13 expression and resistance to Fas-induced apoptosis in ovarian cancer cells lines, which makes difficult to predict the role of PTPN13 in each tumor type." (PMID 29221157, 2017). "On one hand, PTPN13 dephosphorylates signal transducers and activators of transcription that are able to regulate EMT in ovarian cancers." (PMID 31938048, 2020). "Mechanistically, PTPN13 dephosphorylates the signaling domain of HER2 and the phosphorylation of tyrosine 42 on IκBα (IκBα-pY42), respectively, thereby attenuating the invasiveness and metastasis of ovarian cancer." (PMID 35957898, 2022).
prostate carcinoma (8 papers, 2015 to 2026). A carcinoma that arises from epithelial cells of the prostate gland. "PTPN13 downregulation also increases PC3 cell (prostate cancer) invasion through the Matrigel-coated membrane and upregulates invasion-related genes." (PMID 37895093, 2023). "Specifically, PTPN13 suppresses the proliferation and migration of prostate cancer cells and stimulates apoptosis mediated by PKCδ." (PMID 35957898, 2022). "In prostate cancer samples (n = 76), PTPN13 expression, estimated by IHC, was inversely correlated with the Gleason score (p < 0.05)." (PMID 33322542, 2020). "Finally, they reported that PTPN13 and PKCδ expression are lost in poorly differentiated, more aggressive human prostate cancer specimens, suggesting a correlation between their absence, apoptosis resistance and tumor progression." (PMID 33322542, 2020). "In addition, knock-down of PTPN13 in prostate cancer cell lines increases G0/G1 phase cells and decreases S and G2/M phase cells, also suggesting that PTPN13 activity modulates cell cycle progression." (PMID 25436983, 2015). "In contrast, PTPN13 and PTPN14 function as tumor suppressors in prostate cancer." (PMID 35957898, 2022). "Furthermore, siRNA-mediated PTPN13 silencing in the PC3 and DU145 prostate cancer cell lines leads to overexpression of urokinase-type plasminogen activator (uPA) fibrinolytic system components that can degrade the extracellular matrix, thus promoting tumor invasion." (PMID 33322542, 2020).
colon carcinoma (7 papers, 2004 to 2023). "PTPN13 interacts with SDCCAG3 via the FERM domain to regulate cytokinesis in colon cancers." (PMID 33051595, 2021). "More recently, they showed that increased PTPN13 expression characterizes CD133+ colon cancer stem cells and that PTPN13 upregulation in metastases, compared with primary tumors or after platinum-based chemotherapy, is due to the relative abundance of these cancer stem cells in the tumor." (PMID 33322542, 2020). "For instance, in HCT116 colon cancer cells, PTPN13 inactivates SRC through interaction with reversion-induced LIM domain protein (RIL), and in A549 pulmonary and Caco-2 colon adenocarcinoma cells, it inhibits the ERBB3/ERBB2 receptors through association with nectin-like molecule 2 (NECL2)." (PMID 33322542, 2020). "Interestingly, when comparing the expression of ENTR1/PTPN13 with Fas a significant proportion of colon cancer samples exhibit upregulated ENTR1 or PTPN13 and concomitantly downregulation of Fas expression levels." (PMID 31308371, 2019). "This prompted us to investigate expression levels of ENTR1, PTPN13 and Fas in colon cancer samples." (PMID 31308371, 2019). "We found Irf2 repressed PTPN13 transcription in SW620 colon cancer cells." (PMID 29899829, 2018). "In colon cancer cells, where the FAS receptor is strongly expressed, a study showed that PTPN13 silencing with siRNA improves their sensitivity to oxaliplatin by increasing FAS-induced apoptosis." (PMID 37895093, 2023). "Moreover, the FERM domain allows the interaction of PTPN13 with other proteins, such as serologically defined colon cancer antigen 3/endosome-associated trafficking regulator 1 (SDCCAG3/ENTR1) that is overexpressed in colon cancer and is involved in cytokinesis regulation." (PMID 33322542, 2020). "In colon cancer cells, where FAS receptor is strongly expressed, a study showed that oxaliplatin induces PTPN13 expression, thereby protecting cells from apoptosis." (PMID 33322542, 2020). "78% of the colon cancer samples with elevated ENTR1 and 73% of the colon cancer samples with elevated PTPN13 showed downregulation of Fas expression." (PMID 31308371, 2019). "PTPN13 promoter activity (encoding Fap1) was repressed by interferon regulatory factor 2 (irf2), and expression of Fap1 and Irf2 were inversely correlated in CD133+ or CD133− colon cancer cells." (PMID 29899829, 2018). "Furthermore, a recent study demonstrates that uncoupling binding of Fas to PTPN13 by adding a peptide derived from the PDZ binding motif of Fas restores Fas sensitivity and decreased the growth of colon cancer xenografts in a mouse cancer model." (PMID 31308371, 2019). "We confirmed our previous finding that ENTR1 is upregulated in colon cancer tumours compared to non-tumorous tissue, similarly we also observed elevated PTPN13 expression in colon cancer tissue samples, whereas Fas expression was downregulated." (PMID 31308371, 2019).
non-small cell lung carcinoma (6 papers, 2014 to 2024). A group of at least three distinct histological types of lung cancer, including non-small cell squamous cell carcinoma, adenocarcinoma, and large cell carcinoma. "PTPN13 a tumor suppressor is often inactivated in non-small cell lung cancer due to the loss of either mRNA and protein expression or somatic mutation." (PMID 24894543, 2014).
diffuse large B-cell lymphoma (5 papers, 2015 to 2024). "Promoter hypermethylation of PTPN6 and PTPN13 was reported to inhibit the progression of diffuse large B cell lymphomas." (PMID 32536826, 2020). "It has been noted that diffuse large B-cell lymphomas are prevented from progressing by the hypermethylation of the PTPN6 and PTPN13 promoters." (PMID 36699453, 2022).
head and neck cancer (5 papers, 2012 to 2023). A primary or metastatic malignant neoplasm affecting the head and neck. "Altogether, these data indicate that PTPN13 regulates phosphorylation of ephrinB1, which preferentially associates with ERBB1 in head and neck cancer, and allows MAPK pathway activation." (PMID 33322542, 2020). "Importantly, previous studies focused on human papillomavirus (HPV)-associated head and neck cancers demonstrate that the HPV16 E6 oncoprotein binds and targets PTPN13 for degradation." (PMID 22279592, 2012).
leukemia (5 papers, 2018 to 2022). A malignant (clonal) hematologic disorder, involving hematopoietic stem cells and characterized by the presence of primitive or atypical myeloid or lymphoid cells in the bone marrow and the blood. "In addition, the Tel-PGFRβ fusion protein, which results from a chromosomal translocation associated with leukemia, inhibits binding of the Tel/ICSBP/HDAC3 complex to the PTPN13 promoter." (PMID 33322542, 2020).
lung adenocarcinoma (4 papers, 2017 to 2024). A carcinoma that arises from the lung and is characterized by the presence of malignant glandular epithelial cells. "We next analyzed RNA-Seq expression data from TCGA and found that PTPN13 expression changes were not liver-specific, as it was also downregulated in invasive breast carcinoma, thyroid carcinoma, lung adenocarcinoma (LAC), and stomach adenocarcinoma." (PMID 33051595, 2021).
melanoma (4 papers, 2013 to 2026). A malignant, usually aggressive tumor composed of atypical, neoplastic melanocytes. "In addition, the expression of AFF1, PIM1, PTPN13 and TXNIP was downregulated in UV-irradiated FM SFs with a R87P-CDKN2A mutation, and the expression of these genes was also found to be downregulated in melanoma tissue." (PMID 23371019, 2013).
pulmonary fibrosis (4 papers, 2021 to 2025). Chronic progressive interstitial lung disorder characterized by the replacement of the lung tissue by connective tissue, leading to progressive dyspnea, respiratory failure, or right heart failure. "Recent studies have shown that genetic defects in PTP-BL, the mouse homolog of concurrent human PTPN13, reduce bleomycin-induced pulmonary fibrosis in mice." (PMID 41301772, 2025). "This study reveals that phaseoloidin promotes autophagy in myofibroblasts through activating AMPK, thereby reducing collagen deposition in pulmonary fibrosis, and exerts anti-pulmonary-fibrosis effects by degrading PTPN13 and relieving myofibroblasts of apoptotic resistance to FasL." (PMID 41301772, 2025). "Furthermore, the enhanced autophagy relieved myofibroblasts’ PTPN13-mediated resistance to FasL-induced apoptosis, allowing lung fibrosis to subside." (PMID 41301772, 2025). "The distinguished antifibrotic effects of the Fab'-conjugated dual siRNA-loaded micelles indicated that NOX4 and PTPN13 might play cooperative roles in developing pulmonary fibrosis." (PMID 33537085, 2021).
squamous cell carcinoma (4 papers, 2015 to 2022). A carcinoma arising from squamous epithelial cells. "PTPN13 is known to inhibit Fas-induced apoptosis, and its down-regulation significantly increased the survival of human papillomavirus infected patients with squamous cell carcinoma." (PMID 34130627, 2021).
adenoma (3 papers, 2019 to 2025). A neoplasm arising from the epithelium. "All investigated and expressed target genes, CDKN1B, PTPN13, RND3, SOX2 and ZEB2, were down-regulated in adenoma compared to normal mucosa of CRC N0, except ONECUT2 and TGFB2, which were up-regulated." (PMID 31623346, 2019). "In contrast to adenoma, investigated target genes CDKN1B, PTPN13, RND3, SOX2 and ZEB2 were up-regulated in CRC N0, except ONECUT2 and TGFB2, which were down-regulated." (PMID 31623346, 2019). "The majority of target genes (CDKN1B, PTPN13, RND3, SOX2 and ZEB2) were down-regulated in adenoma compared to normal mucosa." (PMID 31623346, 2019). "Moreover, PTPN13, SOX2 and ZEB2 showed detectable expression only in two out of 10 adenoma cases, whereas ONECUT2 and TGFB2 were up-regulated." (PMID 31623346, 2019). "Similarly, both of our cases that showed expression of SOX2 (also showing expression of PTPN13 and ZEB2) were adenomas with high-grade dysplasia." (PMID 31623346, 2019). "Moreover, PTPN13, SOX2 and ZEB2 were expressed only in two out of 10 samples of adenoma, so a calculation of statistical significance would not be appropriate." (PMID 31623346, 2019).
breast tumor (3 papers, 2020 to 2024). "We found that genetic deletion of the PTPN13 catalytic domain results in an increased HER2-induced breast tumor development and a more invasive phenotype of resulting tumors." (PMID 31938048, 2020). "In a previous retrospective analysis of breast tumor RNA samples from 291 patients we showed that PTPN13 mRNA expression is an independent prognostic marker of increased overall survival." (PMID 31938048, 2020). "Moreover, PTPN13 expression promoted desmosome formation in MDA-MB-231 cells and in HER2+/BL-wt breast tumors, as revealed by desmoglein and desmoplakin immunostaining." (PMID 31938048, 2020).
Ewing sarcoma (3 papers, 2018 to 2022). A small round cell tumor that lacks morphologic, immunohistochemical, and electron microscopic evidence of neuroectodermal differentiation. "In contrast, oncogenic functions for PTPN13 are suggested by an EWS-FLI1 chromosomal translocation in Ewing’s sarcoma that leads to a strong up-regulation of PTPN13 protein levels, thereby boosting cell growth and motility." (PMID 29439552, 2018). "As VCP/p97 phosphorylation is necessary for PTPN13 midbody localization during cell division, a PTPN13 pro-oncogenic role in Ewing sarcoma, mediated through regulation of cell division, could be suggested." (PMID 33322542, 2020). "Using substrate trapping in vitro and in vivo in the human Ewing sarcoma TC32 cell line, they identified valosin-containing protein (VCP/p97) as a new PTPN13 substrate." (PMID 33322542, 2020). "As PTPN13 expression is not detectable in bone, its relative variation in Ewing sarcoma cannot be assessed." (PMID 33322542, 2020).
head and neck squamous cell carcinoma (3 papers, 2012 to 2023). A squamous cell carcinoma that arises from any of the following anatomic sites: lip and oral cavity, nasal cavity, paranasal sinuses, pharynx, larynx, and salivary glands. "PTPN13 is involved in cancers such as colorectal, breast, lymphomas, and head and neck squamous cell carcinoma." (PMID 37760479, 2023). "Conversely, another study demonstrated PTPN13’s positive involvement in cisplatin sensitivity of head and neck squamous cell carcinoma (WSU-HN6 and CAL-27) cell lines." (PMID 37895093, 2023). "Similarly, knock-down of PTPN13 in the head and neck squamous cell carcinoma cell line, UM-SCC84, resulted in increased EphrinB1 and Erk1/2 phosphorylation (UM-SCC84)." (PMID 22279592, 2012).
lymphoma (3 papers, 2015 to 2025). A malignant (clonal) proliferation of B- lymphocytes or T- lymphocytes which involves the lymph nodes, bone marrow and/or extranodal sites. "Some of these events are specifically related to lymphomas, such as in case 5, which includes nine single-nucleotide events associated with lymphomas, e.g., the p.P925T missense variant in EP300 (COSV54337074), or events in MCL1 and PTPN13." (PMID 40404986, 2025).
viral infections (3 papers, 2021 to 2025). "There have been few studies correlating these genes with viral infections, but the limited literature does associate them with more severe outcomes, particularly PTPN13." (PMID 40981223, 2025).
cervical cancer (2 papers, 2016 to 2019). A primary or metastatic malignant neoplasm involving the cervix. "Notably, viral integrations were found in many genes, including novel recurrent HPV integrations at PTPN13 in cervical cancer." (PMID 27339696, 2016).
clear cell renal cell carcinoma (2 papers, 2020 to 2021). "Very recently, it was demonstrated that PTPN13 also acts as a tumor suppressor in clear cell renal cell carcinoma (ccRCC) where lower PTPN13 expression levels predict shorter survival rate." (PMID 33322542, 2020).
colon adenocarcinoma (2 papers, 2004 to 2020). "In our study, PTPN5 and PTPN7 were found to be correlated with prognosis of colon adenocarcinoma patients, while PTPN6 and PTPN13 were statistically associated with the prognosis of STAD." (PMID 32536826, 2020).
glioblastoma (2 papers, 2018 to 2020). The most malignant astrocytic tumor (WHO grade IV). "In conclusion, compared with healthy tissues, PTPN13 expression is decreased in all tumor types that have been studied, except for glioblastoma." (PMID 33322542, 2020). "In glioblastoma, PTPN13 RNA level was increased compared with normal brain, but this finding was based only on three samples and should be confirmed." (PMID 33322542, 2020).